OR1X1P (olfactory receptor family 1 subfamily X member 1 pseudogene)
Gene: Unprocessed pseudogene on chromosome 5 (176,006,145 to 176,007,387, forward strand). Ensembl gene ENSG00000272494.
Diseases named in the same sentence as OR1X1P in open-access papers:
OR1X1P is named in the same sentence as 1 disease in open-access papers, as found by Europe PMC text mining. Sharing a sentence is not in itself a finding about the gene and the disease. The quoted sentences say what the papers report.
cancer (1 paper, 2021). A tumor composed of atypical neoplastic, often pleomorphic cells that invade other tissues. "Of these genes, six lncRNA (AL360091.3, AL360175.1, AC025254.1, AC093801.1, AC092354.1 and AC016722.1); four pseudogenes (RBM22P2, AC073324.1, OR1X1P, RPL7P52 and MTND5P25) and coding SLC36A2 and SDS and have not previously been shown to be transcripts in cancer." (PMID 34026616, 2021).